IARS2 (isoleucyl-tRNA synthetase 2, mitochondrial)
Description:
Aminoacyl-tRNA synthetase that catalyzes the specific attachment of isoleucine to its cognate tRNA (tRNA(Ile)).
Synonyms: IleRS; FLJ10326; CAGSSS
Tractability: PROTAC: ubiquitination databases record sites on it; its protein half-life has been measured; a small molecule that binds it is known.
Target class: Enzyme; Ligase
Gene: Protein-coding gene on chromosome 1 (220,094,107 to 220,148,041, forward strand). Ensembl gene ENSG00000067704.
Subcellular location: Mitochondrion matrix
Subcellular location (Human Protein Atlas): Mitochondria
Pathways (Reactome):
Metabolism of proteins: Mitochondrial protein degradation; Mitochondrial tRNA aminoacylation
Gene Ontology:
Molecular function: isoleucine-tRNA ligase activity; aminoacyl-tRNA deacylase activity; aminoacyl-tRNA ligase activity; ATP binding; nucleotide binding; tRNA binding
Biological process: isoleucyl-tRNA aminoacylation; mitochondrial translation; tRNA aminoacylation for protein translation; aminoacyl-tRNA metabolism involved in translational fidelity
Cellular component: mitochondrion; mitochondrial matrix
Genetic constraint (gnomAD): Loss-of-function variants: 41 observed, 77.84 expected, observed/expected ratio (o/e) 0.53, 90% interval 0.41 to 0.68. The upper end of that interval is the gene's LOEUF score, 0.68, which puts it in group 2 of 6, group 1 being the genes least tolerant of losing a copy. Missense variants: 751 observed, 876.05 expected, observed/expected ratio (o/e) 0.86, 90% interval 0.81 to 0.91. Synonymous variants: 279 observed, 319.17 expected, observed/expected ratio (o/e) 0.87, 90% interval 0.79 to 0.96.
Gene-disease validity (ClinGen):
ClinGen rates the evidence that IARS2 causes each of these diseases.
mitochondrial disease (autosomal recessive): Definitive.
Leigh syndrome (autosomal recessive): Limited. A progressive neurological disease defined by specific neuropathological features associating brainstem and basal ganglia lesions.
Homologues: Orthologues: chimpanzee IARS2 (99% identical), macaque IARS2 (98% identical), dog IARS2 (89% identical), rabbit IARS2 (89% identical), pig IARS2 (88% identical), mouse Iars2 (83% identical), rat Iars2 (79% identical), guinea pig IARS2 (79% identical), tropical clawed frog iars2 (66% identical), zebrafish iars2 (59% identical), Drosophila melanogaster IleRS-m (37% identical), Caenorhabditis elegans iars-2 (34% identical). Paralogues in human: IARS1 (25% identical), VARS1 (22% identical), VARS2 (22% identical), LARS2 (16% identical), LARS1 (15% identical), MARS1 (12% identical), MARS2 (9% identical).
Diseases named in the same sentence as IARS2 in open-access papers:
IARS2 is named in the same sentence as 45 diseases in open-access papers, as found by Europe PMC text mining. Sharing a sentence is not in itself a finding about the gene and the disease. The quoted sentences say what the papers report.
Leigh syndrome (4 papers, 2018 to 2025). "Mutations in IARS2 are associated with mitochondrial diseases characterized primarily by Leigh syndrome and craniosynostosis and abnormal genitalia syndrome (CAGSSS)." (PMID 39062673, 2024). "Mutations in IARS2 are associated with Leigh syndrome, craniosynostosis and abnormal genitalia syndrome." (PMID 39062673, 2024).
lung carcinoma (4 papers, 2019 to 2024). "The genes Fubp1, Cox6b1, Pon3, Iars2, Ctsd, and Akr1b1 have been previously shown to promote lung cancer proliferation." (PMID 39273313, 2024). "This study preliminarily revealed the important role of IARS2 in lung cancer pathogenesis and provided a solid hypothetical basis for considering IARS2 expression in the diagnosis and treatment of lung cancer." (PMID 31157169, 2019). "IARS2 was highly expressed in NSCLC tissues, and silencing IARS2 could inhibit the activity of lung cancer cells and reduce the tumorigenicity of cancer cells in nude mice." (PMID 34660690, 2021). "IARS2 appears to regulate lung cancer cell proliferation via the AKT/MTOR pathway." (PMID 31157169, 2019). "SC79 partially restored the IARS2 silencing-induced inhibition of lung cancer cell proliferation." (PMID 31157169, 2019). "In this study, IARS2 knockdown promoted mitochondria-dependent apoptosis, suggesting that IARS2 may promote lung cancer cell proliferation and inhibit apoptosis through abnormal activation of AKT/MTOR signaling." (PMID 31157169, 2019). "In summary, our results indicated that IARS2, an ancient protein synthesis enzyme, may play complex regulatory roles in lung cancer, which should be studied in depth." (PMID 31157169, 2019). "Our results help clarify the complex roles of IARS2 in tumorigenesis and suggest that it may be a novel regulator of lung cancer development." (PMID 31157169, 2019). "IARS2 knockdown reduced AKT Ser473 and Thr308 and MTOR phosphorylation levels in lung cancer A549 and H1299 cells." (PMID 31157169, 2019).
non-small cell lung carcinoma (4 papers, 2019 to 2025). A group of at least three distinct histological types of lung cancer, including non-small cell squamous cell carcinoma, adenocarcinoma, and large cell carcinoma. "In non-small cell lung cancer, gastric cancer, melanoma and acute myeloid leukemia, knockout of IARS2 inhibits cell proliferation and promotes apoptosis." (PMID 38956267, 2024). "The oncogene IARS2 could prompt the tumorigenesis of non-small-cell lung cancer." (PMID 34692528, 2021).
cataract (3 papers, 2018 to 2024). Partial or complete opacity of the crystalline lens of one or both eyes that decreases visual acuity and eventually results in blindness. "Ocular findings are amongst the most common features associated with IARS2 loss of function variants in seven out of ten probands affected by bilateral nystagmus and/or cataracts at birth or within the first three years of life." (PMID 30419932, 2018). "Another example of highly specific phenotypes associated with mt-ARSs is mitochondrial isoleucyl-tRNA synthetase (IARS2), which is associated with a condition characterized by cataracts, growth hormone deficiency, sensory neuropathy, sensorineural hearing loss, and skeletal dysplasia (CAGSSS)." (PMID 36553587, 2022). "In two Chinese probands, compound heterozygous IARS2 mutations associated with sporadic pediatric cataracts (c.607G>C, p.Gly203Arg and c.2575T>C, p.Phe859Leu; c.2446C>T, p.Arg816* and c.2575T>C, p.Phe859Leu) were found, representing the mildest clinical presentation among IARS2-related disorders." (PMID 39062673, 2024). "Genetic mutations in IARS2 (OMIM: 612801) on chromosome 1q41 were first described in an extended French-Canadian family with a syndrome abbreviated CAGSSS that is characterised by cataracts, growth hormone deficiency, sensory neuropathy, sensorineural hearing loss, and skeletal dysplasia." (PMID 30419932, 2018).
colon cancer (3 papers, 2019 to 2022). "Knocking down the IARS2 gene inhibits the proliferation of colon cancer RKO cells, increases the proportion of cells in G0/G1 phase, and decreases the proportion of cells in S phase." (PMID 31157169, 2019). "The expression of IARS2 mRNA in human colon cancer tissues is higher than that in surrounding tissues." (PMID 31157169, 2019). "Certain ARSs, such as isoleucyl-tRNA synthetase 2 (IARS2) and lysyl-tRNA synthetase (KRS), have been shown to promote colon cancer development." (PMID 35694271, 2022).
gastric cancer (3 papers, 2019 to 2025). A primary or metastatic malignant neoplasm involving the stomach. "IARS2 knockdown significantly inhibits the proliferation and colony formation ability of gastric cancer AGS cells and induces cycle arrest at G2/M phase." (PMID 31157169, 2019). "In gastric cancer AGS cells, IARS2 knockdown inhibits proliferation and colony formation and induces cell cycle arrest in the G2/M phase." (PMID 31157169, 2019).
diabetes (2 papers, 2015 to 2025). "This transcription factor leads to the inhibition of FHL1, IARS2, ARL6IP5, PSIP1 and PRPS1, some of which have been implicated in processes that are involved in the progression of different conditions leading to diabetes." (PMID 26302420, 2015). "KEGG enrichment results showed that pathways relating to pancreatic secretion, diabetes, and amino acid metabolism were enriched, indicating that IARS2 might be involved in digestion and glucose regulation." (PMID 40092487, 2025).
infantile spasms (2 papers, 2018 to 2024). A rare epilepsy syndrome characterized by onset of epileptic spasms in infants between 2 and 12 months of age, and rarely up to 24 months. "The patients with IARS2 variants present broad clinical phenotypes including LS, West syndrome and CAGSSS syndrome (cataract, growth hormone deficiency, sensory neuropathy, sensorineural deafness-skeletal dysplasia syndrome)." (PMID 39169373, 2024).
Adrenal insufficiency (1 paper, 2018). Insufficient production of steroid hormones (primarily cortisol) by the adrenal glands. "It would be particularly interesting for additional patients with IARS2 pathogenic variants to be monitored for adrenal insufficiency." (PMID 30419932, 2018).
breast carcinoma (1 paper, 2020). "Some of the screened proteins, like RPS3, GDI2, IARS2, were less investigated and their cancer-related mechanism and roles remain unclear in breast cancers." (PMID 33194682, 2020).
colorectal cancer (1 paper, 2025). A primary or metastatic malignant neoplasm that affects the colon or rectum. "IARS2 is a mitochondrial Isoleucyl‐tRNA synthetase, while AHCYL1 is an adenosylhomocysteine hydrolase‐like protein 1, whose expression was proposed to be considered as a novel biomarker for predicting prognosis and immunotherapy response in colorectal cancer." (PMID 40952239, 2025).
dementia (1 paper, 2022). Loss of intellectual abilities interfering with an individual's social and occupational functions. "Furthermore, isoleucine is a metabolite linked to genes involved in neurological disorders, such as dementia and seizures: BCAT1, BCAT2, and IARS2 (26980008 and 30098844)." (PMID 35629950, 2022).
glioblastoma (1 paper, 2019). The most malignant astrocytic tumor (WHO grade IV). "The expression of IARS2 in short-term survivors of glioblastoma is higher than that in long-term survivors, suggesting that high IARS2 expression is a risk factor for glioblastoma." (PMID 31157169, 2019).
pancreatic cancer (1 paper, 2025). "Kaplan–Meier curves showed pancreatic cancer patients with higher IARS2 expression had shorter overall survival time (P = 0.02) and disease-free survival time (P = 0.01)." (PMID 40092487, 2025). "Irrelevant to patient gender or age, IARS2 transcription level was significantly higher in pancreatic cancer at tumor grade 3–4 compared with grade 1–2 (P = 0.02)." (PMID 40092487, 2025).
squamous cell carcinoma (1 paper, 2019). A carcinoma arising from squamous epithelial cells. "IARS2 expression was higher in NSCLC tissues, and the high expression rate of adenocarcinoma accounted for 72.73%, which was slightly higher than that of squamous cell carcinoma." (PMID 31157169, 2019).
cancer (6 papers, 2019 to 2025). A tumor composed of atypical neoplastic, often pleomorphic cells that invade other tissues. "First, we evaluated the IARS2 transcription level in different cancers using the TCGA database and identified that IARS2 was an oncogene and up-regulated in PDAC." (PMID 40092487, 2025). "Involved in multiple cellular activities, WNT signaling pathway was activated at an early stage of PDAC development and played an important role in stemness maintenance of cancer cells, which prompted us to explore the correlation between IARS2 and stemness." (PMID 40092487, 2025). "IARS2, a protein ligating isoleucine with nucleotide triplets of tRNA, is highly expressed in multiple cancers and promotes tumorigenesis in various organs, but its function in PDAC is unclear." (PMID 40092487, 2025). "Our cDNA microarray analysis revealed highly significant overlap of 353 IARS2-regulated canonical pathways connected with apoptosis, cancer, cell cycle regulation, and cellular immune responses, and cellular growth, proliferation, and development." (PMID 31157169, 2019). "EMT is a key event in cancer stemness, metastasis, and chemotherapy resistance, so we speculate IARS2 promotes PDAC development via EMT, which also partially explains why IARS2 is correlated with poor prognosis." (PMID 40092487, 2025). "Additionally, COX7B, IARS2, COA3 and NDUFA1 were associated with platinum resistance, cancer cell proliferation and invasion, highlighting their significance as potential therapeutic targets and prognostic biomarkers." (PMID 38534098, 2024). "PDAC cancer stem cell markers including CD44, MET, CD133, FUT4, ACVR1, mTOR, and KLF4 were positively related to IARS2 expression." (PMID 40092487, 2025).
mitochondrial disease (4 papers, 2018 to 2024). "In recent years, mutations in both alleles of IARS1 and IARS2 have been linked to mitochondrial diseases." (PMID 39062673, 2024). "This review aims to explore the relationship between IARS1 and IARS2 and these diseases, providing a comprehensive overview of their association with mitochondrial diseases." (PMID 39062673, 2024). "Although no other endocrine disorders have been connected to other patients with mutations in IARS2, mitochondrial disease itself represents a high risk for a variety of endocrine diseases." (PMID 30419932, 2018). "The pathogenic mechanism of mitochondrial diseases caused by IARS2 mutations is primarily related to impaired protein synthesis within the mitochondria, but the details remain largely unknown." (PMID 39062673, 2024). "Mutations in IARS1 and IARS2 have recently been linked to mitochondrial diseases." (PMID 39062673, 2024). "As a result, normal stature does not rule out the possibility of IARS2 variants in mitochondrial diseases." (PMID 38229969, 2024).
tumor (4 papers, 2015 to 2025). "We found higher IARS2 expression in the tumor tissues, which was associated with the late Tumor and Node stages of the Tumor, Node, Metastasis staging system." (PMID 31157169, 2019). "CD8 T cells in PDAC were linked with cytotoxic effects on tumor cells, thus IARS2 might exert immune suppression in the tumor microenvironment of PDAC." (PMID 40092487, 2025). "Next, we investigated the in vivo effect of IARS2 in tumor proliferation by subcutaneous xenograft assays in nude mice." (PMID 40092487, 2025). "Tumor size was measured each other day and the growth curve showed IARS2 overexpression boosted tumor growth (P = 0.03), while knockdown exhibited opposite effect (P = 0.01)." (PMID 40092487, 2025). "IARS2 mainly catalyzes tRNA aminoacylation and correlates with malignant proliferation and apoptosis resistance of tumor cells." (PMID 38956267, 2024). "Additionally, more PDAC tissue and corresponding clinical information of patients should be collected for further validation of the impact that IARS2 exerted on tumor immune microenvironment and metastasis." (PMID 40092487, 2025). "Considering that CD8 T cells were responsible for anti-tumor responses, we speculated that high IARS2 expression could correlate with immunosuppressive microenvironment." (PMID 40092487, 2025). "In mice with IARS2-silenced cells, tumor growth was slower than in the control group." (PMID 31157169, 2019). "There are few reports on the relationship between IARS2 and disease; its role in tumor development remains unclear." (PMID 31157169, 2019). "IARS2 silencing was also found to inhibit NSCLC tumor growth in nude mice." (PMID 31157169, 2019). "We evaluated IARS2 protein expression in lung tumor tissues and paired non-tumor tissues." (PMID 31157169, 2019). "Additionally, we explored the correlation between IARS2 and tumor immune microenvironment." (PMID 40092487, 2025). "In this study, we found that IARS2 is highly expressed in NSCLC tissues, particularly in adenocarcinoma patients and in tumor T and N stages." (PMID 31157169, 2019). "Moreover, we were able to validate the expression of 16/57 differentially expressed proteins in MDCKYBX1 tumour xenografts, some of which were mitochondrial (ACADSB, SLC25A1, IARS2, and OAT)." (PMID 25980435, 2015).
skeletal dysplasia (2 papers, 2018 to 2020). Any Mendelian diseases that affects growth and development of the skeleton. "The first report of CAGSSS, an autosomal recessive syndrome with cataracts, short-stature secondary to growth hormone deficiency, hearing loss, peripheral neuropathy, and skeletal dysplasia, was described in three patients with variants in IARS2." (PMID 33171986, 2020). "Moreover, it is now clear that pathogenic variants in IARS2 are indeed causative and directly linked to the skeletal dysplasia phenotype, as multiple examples of homozygous and compound heterozygous missense mutations have been described." (PMID 33171986, 2020).
endocrine disorders (1 paper, 2018). "The unusual combination of findings suggest that other endocrine disorders in patients with an IARS2-associated mitochondriopathy could likewise be possible and should be excluded." (PMID 30419932, 2018).
IARS2 also shares sentences with these, for which no sentence is quoted: acute myeloid leukemia (2 papers); neurological disorders (2); adenocarcinoma (1); cervical cancer (1); cholangiocarcinoma (1); craniosynostosis (1); diffuse large B-cell lymphoma (1); epilepsy (1); hypoparathyroidism (1); leukemia (1); leukodystrophies (1); lymphoid neoplasm (1); melanoma (1); Nystagmus (1); osteosarcoma (1); ovarian failure (1); pancreatic adenocarcinoma (1); Perrault syndrome 4 (1); polyneuropathy (1); Pure red cell aplasia (1); sensorineural hearing loss with (1); Sensory neuropathy (1); sideroblastic anemia (1); thymoma (1); type 2 diabetes (1).